PAX8 (paired box 8)
Diseases named in the same sentence as PAX8 in open-access papers (continued):
Sharing a sentence is not in itself a finding about the gene and the disease.
follicular thyroid carcinoma (continued). "The most common genetic mutations in papillary and follicular thyroid cancers are point mutations of the BRAF or RAS genes, while the most common chromosomal alterations are RET/PTC and PAX8/PPARγ rearrangements." (PMID 29721199, 2018). "A chromosomal rearrangement of the PAX8 gene with PPARγ (PAX8–PPARγ) is observed in about 36–50% of follicular thyroid cancer cases and 0.8% of papillary thyroid cancer." (PMID 29085335, 2017). "Fusions defining subtypes within a cancer include RET and NTRK gene fusions in subsets of papillary thyroid carcinoma, while PAX8-PPARγ fusions characterize subsets of follicular thyroid carcinoma." (PMID 26684754, 2015). "Recent studies in this field demonstrated PAX8/PPARγ rearrangement in 25%-63% of patients with follicular carcinoma and 37.5% of those suffering from papillary carcinoma." (PMID 23815863, 2013). "With regard to its link to tumour development, Pax8 expression decreases or is lost in follicular thyroid carcinomas as well as in oncogene-transformed thyroid cells." (PMID 22531031, 2012). "PAX8/PPARγ is found in 30–40% of conventional-type follicular carcinomas, and with lower prevalence in oncocytic carcinomas in a small fraction of follicular adenomas and occasionally in the follicular variant of papillary carcinoma." (PMID 22654559, 2011). "It is most often expressed in follicular carcinomas and exerts a dominant-negative effect on wild-type PPARγ, and stimulates transcription of PAX8-responsive promoters." (PMID 18989374, 2008). "Paired box gene 8 is necessary for the formation of thyroxine-producing follicular cells in the thyroid gland; and fusion of the Pax-8 and peroxisome proliferator-activated receptor γ (PPARγ) genes occurs in approximately 30% of follicular thyroid carcinomas." (PMID 18682709, 2008). "The recent discovery of the PAX8/PPARγ translocation in follicular thyroid carcinoma has promoted progress in the role of PPARγ as a tumor suppressor and potential therapeutic target." (PMID 18989374, 2008). "In the case of thyroid follicular cancer, a chromosomal translocation and fusion of PAX8 gene with PPARγ results in a malignant phenotype, suggesting a link of PPARγ to cancer growth." (PMID 15583697, 2005). "Thyroid follicular cancer presents either the RAS mutation or the PAX8-PPAR gamma 1 rearrangement, but not both." (PMID 39744583, 2025). "It has been reported that follicular adenomas with the PAX8/PPARγ rearrangement are likely to be follicular carcinomas, as these genetic abnormalities are presumed to be involved in the progression from follicular adenoma to follicular carcinoma." (PMID 38791384, 2024). "Notably, PAX8-PPARG chimeric gene, associated to follicular carcinomas, has been reported with low frequency in PTC." (PMID 25803323, 2015). "RAS genes and PAX8/PPARγ rearrangement are found more in follicular carcinomas." (PMID 23717622, 2013). "PAX8/PPARgamma translocations are found predominantly in follicular thyroid carcinomas." (PMID 24281099, 2010). "As a biomarker, a PAX8/PPARgamma rearrangement is a strong indicator that a tumor is a follicular carcinoma with an early propensity for vascular invasion, but it is not sensitive or specific enough to be used on its own to reliably distinguish between benign and malignant follicular neoplasms." (PMID 24281099, 2010). "Recent studies demonstrated that screening for RAS, RET/PTC, and PAX8/PPARγ gene alterations in addition to BRAFV600E provided significant improvement in the diagnostic accuracy of FNA cytology, particularly in the categories of indeterminate cytology and follicular carcinomas." (PMID 34851044, 2022). "A chromosomal translocation fusing the genes PAX8 and PPARG is found in 30% of follicular thyroid carcinomas." (PMID 28008156, 2017). "Co-transfection of Pax-8 and TTF-1 restored TG promoter activity in WRO (follicular thyroid carcinoma) and ARO cells." (PMID 18682709, 2008).
follicular thyroid carcinoma (continued). "Rearrangement of the RET and PAX8-PPARγ1 gene is found frequently in papillary and follicular carcinomas, respectively, but not in anaplastic carcinomas." (PMID 17453004, 2007).
thyroid (37 papers, 2012 to 2026). "PAX8 knockout mice demonstrate that thyroid hypoplasia, low birth weight and growth retardation, and genetic mutations in PAX8 can cause CHT in humans." (PMID 34739318, 2021). "PAX8 mutations cause thyroid dysgenesis and some mutations were compatible with dyshormonogenesis as already described." (PMID 33692749, 2020). "Collectively, these findings point to significant PTC-associated dysregulation of several PAX8 target genes, supporting the notion that PAX8-regulated molecular cascades play important roles during thyroid tumorigenesis." (PMID 27249794, 2016). "And mutations in thyroid transcription factors TTF-1, TTF-2 and PAX-8 have been implicated in thyroid dysgenesis and abnormal migration of the thyroid bud." (PMID 24748408, 2014). "Differences in genetic background could explain phenotypic variations of thyroid dysgenesis although the pathogenetic mutations are identical as in Nkx2-1/Pax8 compound heterozygous mice." (PMID 29361553, 2018). "In this large cohort of thyroid dysgenesis with CH in a Chinese population, we identified several novel PAX8 mutations and functionally characterized two in functionally critical domain of PAX8—D94N and G41V." (PMID 28060725, 2017). "Also, the association between mutations of PAX8 and congenital hypothyroidism in humans underlines an important function of this transcription factor in thyroid pathologies." (PMID 22531031, 2012). "In lung carcinoma, while the oncogenic role of PAX8 is yet to be explored, it is crucial in the diagnostic workup for distinguishing primary tumors from metastases, especially in cases resembling other PAX8-positive cancers (e.g., thyroid or renal cancers)." (PMID 40506992, 2025). "In mediastinal mass biopsies, PAX8 is crucial in the diagnostic workup for distinguishing primary tumors from metastases, particularly in cases that resemble other PAX8-positive cancers (e.g., thyroid or renal cancers)." (PMID 40506992, 2025). "Pax8 and Ttf1 are transcription factors crucial to thyroid organogenesis, and their absence results in varying degrees of thyroid dysgenesis." (PMID 36765847, 2023). "According to previous reports, the cause of CH in approximately 80%–85% of patients is thyroid dysgenesis (including agenesis, ectopy, and hypoplasia), which is related to gene mutations in TSHR, PAX8, TTF1/NKX2-1, and TTF2/FOXE1." (PMID 37252044, 2023). "PAX8: Monoallelic, pathogenic PAX8 variants classically cause thyroid hypoplasia, however, almost 30% affected cases have GIS CH, and a minority exhibit thyroid ectopy or athyreosis." (PMID 35999191, 2022). "The 11 selected thyroid-specific RNA transcripts (TPO, TG, GFRA2, IYD, PDE8B, WDR86, C16orf89, DGKI, DIO2, TSHR, and PAX8) were amplified from healthy volunteers and thyroid patients." (PMID 34512731, 2021). "Thyroid dysgenesis is caused by genes (thyroid transcription factor-1 [TTF-1], thyroid transcription factor-2 [TTF-2], and paired box 8 [PAX-8]) associated with syndromic CH and those causing non-syndromic CH (thyroid-stimulating hormone receptor [TSHR])." (PMID 34638176, 2021). "Wealso identified hypermethylation in the gene body of PAX8 (OMIM 167415), variants in which cause congenitalhypothyroidism due to thyroid dysgenesis or hypoplasia (OMIM 218700)." (PMID 31949313, 2020). "As a major specific regulator of the thyroid gland, the role of PAX8 in thyroid dysgenesis has drawn particularly considerable attention." (PMID 28060725, 2017). "In conclusion, our study provides evidence of significant dysregulation of several putative PAX8 target genes in PTC, supporting the notion that PAX8-regulated molecular cascades play important roles in thyroid tumorigenesis." (PMID 27249794, 2016). "To gain further insight into the roles played by PAX8 target genes during thyroid tumorigenesis, we investigated their expression in a cohort of PTCs with well characterized clinicobiological features." (PMID 27249794, 2016).
thyroid (continued). "The Pax8/Titf1 murine model exemplifies the role of polygenicity in thyroid dysgenesis because only mice doubly heterozygous for the two null alleles and bred on a C57BL/6 background exhibit a phenotype." (PMID 27525530, 2016). "Intriguingly, Pax8 modulates the expression of several genes involved in carcinogenesis and thyroid malignancies (phosphatidyl-inositol/insulin and MAPK pathways) and cell cycle processes (CDKN2BCCNB1 and CCNB2, among others)." (PMID 22531031, 2012). "However, a significant decrease in PAX8 expression was observed in both primary tumors and metastatic lesions compared to normal thyroid tissues, suggesting a potential role for PAX8 down-regulation in thyroid tumorigenesis." (PMID 40506992, 2025). "Thyroid dysgenesis has been primarily associated with mutations in genes such as those encoding the TSH receptor (Tshr), Forkhead box protein E1 (Foxe1), and the Paired box protein Pax-8 (Pax8)." (PMID 34502288, 2021). "Paired box 8 (PAX8) is an important TF in thyroid tumorigenesis." (PMID 31200515, 2019). "However, the tumor was unequivocally negative for thyroid-associated markers such as TTF1, PAX8 and thyroglobulin, setting it apart from other thyroid-related salivary gland tumors that are not uncommonly positive for one or several of these proteins." (PMID 32519264, 2021). "The tumor expressed thyroid markers (TTF-1, PAX-8, thyroglobulin) and renal cell markers (colloidal iron, parvalbumin, CD117) with peripheral mitochondrial accentuation by anti-mitochondrial staining." (PMID 41518426, 2026). "Pathological examination and IHC analysis provide conclusive evidence for diagnosis, in which the tumor’s positive response to thyroid-specific markers, such as TTF-1, PAX8, and thyroglobulin, is key to diagnosis." (PMID 41244794, 2025). "The genes associated with thyroid morphogenesis such as NKX2-1, NKX2-5, PAX8, FOXE1, and thyroid-stimulating hormone receptor (TSHR) have been reported to be involved in thyroid dysgenesis." (PMID 32394050, 2020). "We investigated and correlated c-KIT expression levels and two known markers of thyrocytes differentiation, PAX8 and TTF-1, in malignant and benign cytological thyroid samples." (PMID 28301608, 2017). "As PAX8 is also expressed in a wide variety of neoplasms from other organs, an initial panel of TTF-1, TG, and PAX8 is needed to confirm or exclude distant metastases from a thyroid primary." (PMID 37324272, 2023). "Additional markers were ordered, and although the tumor was positive for CD10, CD117, HNF-beta and vimentin, a diagnosis of a thyroid-like follicular carcinoma of the kidney was ruled out based on the overall morphology and a negative PAX8 stain." (PMID 32519264, 2021). "Even given this knowledge on the role of PAX8 in thyroid dysgenesis, its genetic molecular pathogenesis has not been uniformly documented and characterized in different ethnic populations, including the large Chinese population." (PMID 28060725, 2017).
ovarian tumors (29 papers, 2010 to 2025). "Studies on ovarian tumors also employed the expression of transcriptional factor Pax8, involved in the development of the fallopian tube epithelium and the development of Mullerian phenotype cancers (serous, clear cells, and endometroid)." (PMID 38791431, 2024). "Ovarian tumors responsible for OPMP expressed PAX8 in 1/10 (10%) tumors, SATB2 in 3/10 (30%) tumors, CK7 in 6/12 (50%) tumors, and CK20 in 11/12 (91.7%) tumors." (PMID 38341381, 2024). "In contrast, primary ovarian tumors are usually large, multicystic masses with smooth surfaces, seldom infiltrative histology, nuclear expression of PAX8, and dual positivity for CK7 and CK20." (PMID 37900517, 2023). "PAX8 is amplified in 16% of HG-SOC patients and overexpressed in ovarian tumors, suggesting that PAX8 is a lineage-specific essential gene, at least in a subset of OC cases." (PMID 34439181, 2021). "PAX-8 is characteristic for the epithelial phenotypes (serous, clear cell and endometrioid) of ovarian tumors and is useful in differentiation between primary ovarian and metastatic tumors of the ovary." (PMID 33080944, 2020). "We used immunohistochemistry to evaluate PAX8 protein expression in ∼160 primary ovarian tumors representing the four major histotypes of EOC - HGSOC, clear cell ovarian cancer (CCOC), endometrioid ovarian cancer (EnOC) and mucinous ovarian cancer (MOC)." (PMID 29312534, 2017). "Immunofluorescence assays identified EOC ascites spheroids as multicellular structures containing ovarian tumor cells (PAX8+Ki67+) and numerous lymphocytes, such as TAMs (CD68+CD206+, CD68+CD86+), T cells (CD8+), DCs (CD11c+) and NK cells (CD56dim, CD56bright)." (PMID 39198883, 2024). "(E) Confined gene expression of the PAX8 regulon in TCGA ovarian tumor tissues." (PMID 31050342, 2019). "In this case, the ovarian tumor showed positivity for PAX8 and WT1." (PMID 31807285, 2019). "We then performed a phenogenotypic screen using OVTOKO and KURAMOCHI to explore whether manipulating PAX8 regulon genes would impact on ovarian tumor cell viability or motility." (PMID 31050342, 2019). "Interestingly, PAX8 IHC status was in concordance with genomic results in the present model of primary ovarian tumors compared to ovarian metastases from breast cancer, except for one patient who had a clear-cell carcinoma." (PMID 20492709, 2010). "To determine whether the PFD-sEV fraction isolated from oncological patients contained vesicles specifically secreted by the ovarian tumor cells, we evaluated through immunoblotting the expression of the paired box 8 (PAX8) protein in a subset of OvCa cases (n = 13) and controls (n = 7)." (PMID 38564289, 2024). "A cell block analysis of the ascites taken during the operation showed positivity of CK7, ER, and PAX8 and negativity of CK20 and CDX-2, leading to the diagnosis of a possible uterine or ovarian tumor." (PMID 41018407, 2025). "A repeat cell block examination of the ascites taken during the operation showed positivity of CK7, ER, and PAX8 and negativity of CK20 and CDX-2, leading to the diagnosis of a possible uterine or ovarian tumor." (PMID 41018407, 2025). "This case highlights the diagnostic challenges of occult cervical adenocarcinoma mimicking PMP and underscores the critical role of immunohistochemical profiling (p16, PAX8, WT1) to differentiate metastatic from primary ovarian tumors." (PMID 41584594, 2025).
ovarian tumors (continued). "We used seven histologic markers (PAX2, PAX8, ER, PR, WT1, CK20 and CDX2) commonly expressed in other types of ovarian tumors such as serous, mucinous or endometrioid." (PMID 35387670, 2022). "We demonstrate that both PAX8 and MECOM are critical TFs to sustain in vivo growth of ovarian tumors, likely by MECOM acting as a PAX8 cofactor mediating a subset of PAX8 oncogenic functions." (PMID 33903593, 2021). "The samples were macroscopically normal in appearance, however positive staining for the ovarian tumour markers WT1 and Pax8 was observed in four of the 10 samples collected." (PMID 32716937, 2020). "Importantly PAX8 and MECOM are necessary for ovarian tumor growth in vivo and their signature distinguishes a subset of patients with poor prognosis." (PMID 33903593, 2021). "(B and C) FAK pY397 staining intensity of paired patient ovarian tumor samples from initial biopsies and after surgical removal following neoadjuvant chemotherapy within Pax8-positive (tumor) and Pax8-negative (stroma) regions." (PMID 31478830, 2019). "To get insight into the effects of different treatments on ovarian tumor morphology and markers of proliferation and apoptosis, we performed H&E and IHC analysis of representative PDX-0113 tumors tissues with the following antibodies: human cytokeratin (CK), PAX8, pS6, Ki67 and cleaved caspase-3." (PMID 33488949, 2020). "For the sixteen ovarian tumors, PAX8 was deemed positive in six cases, and negative in ten cases." (PMID 20492709, 2010). "In ovarian tumors, PAX2 is detected in clear cell and mucinous tumors, but absent in most endometrioid tumors, while PAX8 shows high expression in clear cell and endometrioid tumors and reduced expression in mucinous tumors." (PMID 35387670, 2022). "In our case, both the ovarian tumor and the tumor in the breast dermis showed similar morphology and immunohistochemistry, positive PAX8, and negative GCDFP-15, suggesting that the dermal breast lesion metastasized from the ovarian tumor as an advanced stage." (PMID 27047697, 2016).